CD38 (CD38 molecule)
Diseases named in the same sentence as CD38 in open-access papers (continued):
Sharing a sentence is not in itself a finding about the gene and the disease.
multiple myeloma (continued). "The overexpression of CD38 on malignant plasma cells makes CD38 an ideal target for immunotherapy in multiple myeloma (MM); and a potential target in adult acute myeloid leukemia (AML) and T-cell acute lymphoblastic leukemia (T-ALL)." (PMID 36581667, 2022). "For example, in malignant myeloma cells, CD38 is required for oxidative phosphorylation and intercellular mitochondrial transfer, yet studies in aging have found that CD38 levels are inversely proportional to mitochondrial function." (PMID 35348641, 2022). "CD38 is highly expressed on normal and malignant plasma cells, making this a particularly attractive target in multiple myeloma (MM)." (PMID 36006226, 2022). "In multiple myeloma (MM), the latest preclinical trial has confirmed that when combined with daratumumab, expanded g-NK cells with low CD38 expression and potent ADCC activity presented dramatically superior curative and persistence than conventional NK cells." (PMID 36428748, 2022). "Adoptive transfer of natural killer (NK) cells with augmented antibody-dependent cellular cytotoxicity (ADCC) capabilities and resistance to CD38 targeting has the potential to enhance the clinical anti-myeloma activity of daratumumab (DARA)." (PMID 35135865, 2022). "In multiple myeloma patients receiving either one of the COVID-19 mRNA vaccines or the vector-based vaccine AZD1222, treatment with anti-CD38 monoclonal antibodies or anti-BCMA ADCs was associated with significantly reduced humoral vaccine response." (PMID 35214642, 2022). "Anti-CD38 monoclonal antibodies (mAbs), daratumumab, and isatuximab have represented a breakthrough in the treatment of multiple myeloma (MM)." (PMID 36581954, 2022). "The CD38‐targeted nanoparticles were taken up fourfold by CD38‐positive myeloma cells than by normal cells and entered target cells through endocytosis, resulting in a much higher drug concentration." (PMID 35665368, 2022). "Multiple myeloma patients have the highest level of CD38 expression (~105) in plasma cells, followed by NK cells (~104)." (PMID 35342342, 2022). "To evaluate which of these proteins is more highly expressed at the myeloma cell surface, we used calibrated flow cytometry to measure absolute antigen density of both CD38 and CD48 expression." (PMID 35840578, 2022). "Binding of #5-CD38-IgG1 to CD38-positive L-363 myeloma cells was compared to daratumumab and isatuximab by flow cytometric analyses with increasing antibody concentrations." (PMID 35784366, 2022). "Daratumumab, an anti-CD38 monoclonal antibody developed to target tumoral plasma cells in multiple myeloma (MM), induces the killing of CD38-bearing cells through different mechanisms of action." (PMID 36052091, 2022). "The promising results of our preclinical studies warrant further clinical studies to evaluate the potential of these CD38-specific nanobody-based constructs for treatment of multiple myeloma." (PMID 36405759, 2022). "Immunotherapy, since the development of anti-CD38, is a milestone in the treatment of myeloma and has already led to many paradigm shifts." (PMID 36225211, 2022). "CD38 and B-cell maturation antigens (BCMAs) are prevalently expressed on neoplastic plasma cells in multiple myeloma (MM), making them ideal therapeutic targets." (PMID 36614086, 2022). "Further analyses revealed that #5-CD38-IgG1 shared an overlapping epitope with daratumumab and isatuximab and had potent anti-myeloma activity comparable to the two clinically approved CD38 antibodies." (PMID 35784366, 2022). "CD45 is as marker of proliferating, immature myeloma cells, whereas CD38 is a marker of terminally differentiated plasma cells and expressed by most MM cells." (PMID 35005550, 2022). "Treatment with daratumumab can rapidly deplete CD38+ Tregs, MDSCs, and Bregs and is associated with clonal expansion of CD4+ and CD8+ T cells in myeloma patients." (PMID 35886976, 2022).
multiple myeloma (continued). "Immuno-positron emission tomography using radiolabeled CD38-specific antibodies overcomes this challenge, thereby enabling the detection and visualization of CD38-expressing myeloma cells in vivo." (PMID 36389758, 2022). "Here we review the utility of these nanobody-based constructs to specifically and effectively target CD38-expressing myeloma cells." (PMID 36405759, 2022). "In the context of multiple myeloma, a high level of expression of CD38 in plasma cells makes it a promising target for monoclonal antibody-based immunotherapy." (PMID 35631621, 2022). "CD38 is expressed on immune cells, overexpressed on myeloma cells, and contributes to cell adhesion and ecto-enzymatic activities." (PMID 36176763, 2022). "Recent studies have demonstrated the feasibility of CD38-specific antibody constructs for in vivo imaging of multiple myeloma." (PMID 36389758, 2022). "In multiple myeloma, CD38 expression is typically high and homogenous, thereby supporting a sustainable therapeutic response." (PMID 36139103, 2022). "The tumorigenic roles of CD38 in myeloma and other hematologic malignancies were highlighted in this review so as to gain a better insight as to the various determinants of response that can be further targeted to enhance CD38-directed antitumor mechanisms." (PMID 36139103, 2022). "Daratumumab (DARA), an anti-CD38 monoclonal antibody (MoAb) has shown potent therapeutic effects for both newly diagnosed and relapsed multiple myeloma (MM)." (PMID 35326392, 2022). "Clinical experience has shown that anti-CD38 antibody therapy is transforming treatment of MM owing to its anti-myeloma efficacy and manageable safety profile." (PMID 35943588, 2022). "Both T-cell ALL and B-lineage ALL cells can overexpress CD38 and are potential targets for treatment with daratumumab, which has been shown to have efficacy in adult cancers, especially in CD38+ multiple myeloma." (PMID 35281233, 2022). "It induces the internalization of CD38 from the myeloma cell surface, sensitizes myeloma cells to bortezomib, triggers antibody-dependent cellular cytotoxicity, antibody-dependent cellular phagocytosis, and complement-dependent cytotoxicity." (PMID 35631621, 2022). "Previous studies demonstrated the feasibility of fluorophore- or radionuclide-labeled daratumumab for in vivo imaging purposes of CD38-expressing myeloma cells." (PMID 36389758, 2022). "Mechanistic insights to antitumoral mechanisms mediated by CD38 antibodies in multiple myeloma are a model to be learnt from and, most importantly, applied and extended to other CD38-dependent malignancies or diseases." (PMID 36139103, 2022). "Daratumumab is a first-in-class, fully human IgG1-kappa monoclonal antibody targeting CD38 that is approved for the treatment of multiple myeloma." (PMID 35631621, 2022). "All-trans retinoic acid (ATRA) has been shown to increase the expression of CD38 on multiple myeloma and acute myeloid leukemia cells." (PMID 36052078, 2022). "Similar effects have been observed for the treatment of multiple myeloma (MM) with CD38-specific Ab, daratumumab." (PMID 35464486, 2022). "Transplanted patient‐derived tumor cells were identified using human‐specific probes/antibodies and enriched in the CD45dim/CD38+/CD56+/CD19‐/CD27+/CD138+or−/cLambda−/cKappa+ myeloma cell population." (PMID 35789025, 2022). "Monoclonal antibodies against CD38 are known to be highly effective in the treatment of multiple myeloma." (PMID 35395951, 2022). "Thereby, the majority of novel anti-myeloma immunotherapeutics target BCMA or CD38 on the cell surface of the malignant plasma cells." (PMID 35784366, 2022). "A lot of studies are focused on the optimization of CD38-targeting antibodies in multiple myeloma, as well as the elucidation of the detailed mechanism of action from the point of patient exposure to the development of a refractory response, and rightly so." (PMID 36139103, 2022).
multiple myeloma (continued). "Given its common expression in multiple myeloma and T-cell malignancies and minimal expression on pluripotent hematopoietic stem cells, CD38 has emerged as an attractive drug target." (PMID 35955734, 2022). "Anti-CD38 antibodies are transforming MM treatment owing to their profound anti-myeloma activity as single agents and in combinations, as well as their manageable safety profiles." (PMID 35943588, 2022). "They all received immunotherapy: anti-CD38 mAb for multiple myeloma (daratumumab, n = 1), anti-CD52 mAb for T-cell chronic leukemia (alemtuzumab, n = 1), and anti-CD19 anti-CD3 bispecific mAb for acute lymphoblastic leukemia (blinatumomab, n = 1)." (PMID 36366475, 2022). "CD24+CD38+ B cells in the bone marrow and peripheral blood of patients with multiple myeloma can inhibit the ADCC displayed by NK cells against myeloma cells." (PMID 35350071, 2022). "Our data show that the high expression of CD38 on myeloma cells make it suitable for using immunotherapy in combination with monoclonal antibody directed against CD38, such as Daratumumab." (PMID 35413499, 2022). "CD38-targeting antibodies are transforming the treatment landscape, particularly for multiple myeloma patients, having demonstrated profound anticancer efficacy coupled with a relatively manageable toxicity profile." (PMID 36139103, 2022). "CD38 is highly expressed on multiple myeloma (MM) cells and plays a role in regulating tumor generation and development." (PMID 35342342, 2022). "CD38 is overexpressed by multiple myeloma and targeting this antigen is under investigation as a treatment for this and other malignancies, but NK cells express CD38, especially when expanded ex vivo." (PMID 35414042, 2022). "Most of the undergoing clinical trials focus on the use of anti-CD38 antibodies in the therapy of multiple myeloma, CD19- B-cell malignancies, and NK cell lymphomas." (PMID 36077708, 2022). "CD38 is a cell surface antigen that is expressed or overexpressed in several different hematologic malignancies including multiple myeloma (MM), T-cell acute lymphoblastic leukemia (T-ALL), and others including some BPDCNs." (PMID 35565416, 2022). "Unfortunately, detecting multiple myeloma in daratumumab-pretreated patients remains difficult due to overlapping binding epitopes of currently available CD38-specific imaging antibody constructs and daratumumab." (PMID 36389758, 2022). "Fluorochrome-labeled nanobody JK36AF680 showed specific binding to CD38-expressing myeloma cells pretreated with daratumumab in vitro and ex vivo and allowed for specific imaging of CD38-expressing xenografts in daratumumab-pretreated mice in vivo." (PMID 36389758, 2022). "Daratumumab, a CD38 monoclonal antibody that has been FDA-approved to treat multiple myeloma, has acquired popularity and is used off-label for both auto- and alloantibody mediated disorders, particularly in refractory/resistant circumstances." (PMID 36524117, 2022). "BiKE-DCC by HLE-nano-BiKEs was shown to rely on binding to both, CD38 on target myeloma cells and CD16 on effector NK cells." (PMID 35651607, 2022). "The results of our own studies with CD38-specific nanobodies illustrate the utility of nanobody-based heavy chain antibodies, BiKEs, CARs and nanobody-displaying AAV vectors to specifically and effectively target CD38-expressing myeloma cells." (PMID 36405759, 2022). "Cell identity was validated using human antibodies and probes consistent with a myeloma origin for example, CD45dim/CD38+/CD56+/CD19‐/CD28+/CD138+or−/cLambda+/cKaappa−." (PMID 35789025, 2022). "Multiple myeloma (MM) is the second most common hematologic tumor, until anti-CD38 antibodies Daratumumab and Isatuximab have been approved for treating multiple myeloma." (PMID 35978433, 2022). "Anti-CD38 antibodies have revolutionized anti-myeloma therapy, utilizing the density of these antigens on MM cells’ surface." (PMID 35407416, 2022).
multiple myeloma (continued). "Despite treatment advances, patients with multiple myeloma (MM) often progress through standard drug classes including proteasome inhibitors (PIs), immunomodulatory drugs (IMiDs), and anti-CD38 monoclonal antibodies (mAbs)." (PMID 35332278, 2022). "Adaptive NK cells mediate antibody-dependent cellular cytotoxicity (ADCC) in multiple myeloma and can be improved by treatment with anti-CD38 mAbs, such as daratumumab and isatuximab." (PMID 36685576, 2022). "All three CD38 antibodies mediated phagocytosis of myeloma cells to a comparable extent with maximum ADCP achieved within 3 h." (PMID 35784366, 2022). "High, uniform expression of CD38 by myeloma cells, combined with its role in cell signaling, demonstrates that CD38 is a viable therapeutic target in myeloma patients." (PMID 35172851, 2022). "This is particularly compatible with the combination treatment of daratumumab against leukemia, as the daratumumab can be selective to CD38 expressed on myeloma cells." (PMID 36445164, 2022). "CD38 is highly expressed in multiple myeloma and some ALL and AML blasts, with findings of persistent expression even after chemotherapy exposure." (PMID 35955734, 2022). "CD38 is one of the targets due to its high expression in many hematological malignancies, including multiple myeloma, ALL and a subset of AML." (PMID 36313735, 2022). "In contrast, in an assay using DARA-treated CD38+ NCI-H929 myeloma cells, CD38KO NK cells transfected with CD16-158V mRNA displayed greater cytotoxicity than both CD16-158V-transfected CD38WT NK cells and non-transfected CD38KO NK cells." (PMID 35135865, 2022). "Even if the anti-CD38 daratumumab has been approved in multiple myeloma patients and preclinically assessed against T-ALL, a careful clinical monitoring is required for on-target off-tumor toxicities in these frail patients." (PMID 35740552, 2022). "Life expectancy of multiple myeloma (MM) patients has improved in last years due to the advent of anti-CD38 monoclonal antibodies in combination with immunomodulators and proteasome inhibitors." (PMID 35928865, 2022). "Daratumumab and isatuximab are CD38-specific monoclonal antibodies that have been approved for the treatment of multiple myeloma in newly diagnosed and relapsed myeloma patients." (PMID 36405759, 2022). "A phase I dose escalation study was conducted in a cohort of ten patients with CD38+ multiple myeloma." (PMID 36006226, 2022). "A wide range of laboratory experiments and clinical trials show an especially promising role of anti-CD38 therapy against multiple myeloma, NK cell lymphomas, and CD19- B-cell malignancies." (PMID 36077708, 2022). "One novel antibody targeted the well-established myeloma antigen CD38 and was converted into a chimeric IgG1." (PMID 35784366, 2022). "Dexamethasone is a corticosteroid used to suppress inflammation and is approved in combination with the anti-CD38 antibody daratumumab and bortezomib for the treatment of multiple myeloma." (PMID 36560403, 2022). "Patients treated with daratumumab (Dara, hereafter), a monoclonal antibody targeting CD38 on multiple myeloma, showed a decrease in NK cells number." (PMID 35449580, 2022). "The possibility to detect and monitor CD38-expressing myeloma cells in daratumumab-pretreated patients is of increasing importance considering the increasingly broader indications for daratumumab treatment." (PMID 36389758, 2022). "The efficacy of anti-CD38 therapy was proved against multiple myeloma, NK cell lymphomas, and CD19- B-cell malignancies in various clinical trials and laboratory experiments." (PMID 36077708, 2022). "High expression on multiple myeloma (MM) cells and limited expression on normal cells makes CD38 an ideal target for the treatment of MM patients." (PMID 35943588, 2022). "Daratumumab, a monoclonal antibody directed against CD38 is a recent class of drugs introduced into the multiple myeloma therapeutic landscape." (PMID 35251992, 2022).
multiple myeloma (continued). "The CD38 antibody daratumumab is an example of how individual antibodies can change the therapeutic landscape, in this case for multiple myeloma patients." (PMID 36052078, 2022). "Immune-based therapies, starting with the emergence of anti-CD38 monoclonal antibodies, whose impact is seen across all groups of patients, are probably the greatest evolution in the field of myeloma so far." (PMID 36225211, 2022). "Remarkably, AAVs displaying a CD38-specific nanobody also specifically transduced CD38-expressing myeloma cells in primary bone marrow samples of multiple myeloma patients." (PMID 36405759, 2022). "In a study of cocultures of BMSCs and multiple myeloma cells, it was found that CD38 mediates the formation of TNTs, while inhibiting CD38 led to mitochondrial transfer reduction in-vitro and in-vivo." (PMID 35590379, 2022). "Our CD38-specific HLE-nano-BiKEs all showed specific binding to CD38 on myeloma cells, CD16 on NK cells, and to human albumin." (PMID 35651607, 2022). "In this review we focused on the applicability of CD38-specific nanobody-based constructs for the treatment of multiple myeloma." (PMID 36405759, 2022). "Daratumumab is a human specific IgG1 anti-CD38 antibody, which has been approved as a single drug or combined regimen for the treatment of recurrent/refractory multiple myeloma." (PMID 35251964, 2022). "Daratumumab is a humanized anti-CD38 IgG1k monoclonal antibody with FDA approval for treatment of multiple myeloma and many ongoing studies in T-cell malignancies." (PMID 35955734, 2022). "For instance, isatuximab is known to more efficiently induce programmed cell death (PCD) of myeloma cells and to inhibit the enzymatic activity of CD38 than daratumumab, while daratumumab in contrast to isatuximab potently induces CDC." (PMID 35784366, 2022). "Paired PB and BM samples were collected from newly diagnosed, treatment-naïve myeloma patients (n = 19) and patients progressing during treatment with the CD38 monoclonal antibody daratumumab alone or in combination with other anti-myeloma drugs (n = 39)." (PMID 36131131, 2022). "These hcAbs showed potent ADCC toward CD38 expressing tumor cell lines in vitro and to multiple myeloma cells from patient bone marrow samples ex vivo independent of the bound epitope, but failed to induce CDC of these cells." (PMID 36405759, 2022). "CD38 antibodies kill myeloma cells via antibody-dependent cell-mediated cytotoxicity, complement-dependent cytotoxicity, antibody-dependent cell-mediated phagocytosis as well as the direct apoptosis of CD38+ MM cells via FcγR-mediated crosslinking." (PMID 35631621, 2022). "Daratumumab is a first-in-class, IgG1κ human CD38-targeting monoclonal antibody first approved by FDA for the treatment of multiple myeloma (MM) in 2015." (PMID 36139103, 2022). "These patients also demonstrated increasing T cell responses against CD38 and clinical myeloma responses to treatment." (PMID 35943588, 2022). "Daratumumab, an anti-CD38 monoclonal antibody developed to target malignant plasma cells in multiple myeloma, was also reported to effectively treat refractory post-HSCT AIC in several recent case reports." (PMID 35693771, 2022). "The anti-myeloma benefit of daratumumab can be potentiated when combined with bortezomib which leads to increased expression of CD38 target on MM cells." (PMID 36176763, 2022). "Daratumumab (DARA) is a CD38 antibody approved for the treatment of MM as monotherapy or in combination with a number of standard of care anti-myeloma drugs." (PMID 36359760, 2022). "In multiple myeloma (MM), CD38 antigen is expressed on plasma cells to a higher degree than physiologically." (PMID 36077708, 2022). "In multiple myeloma, the kinetics of therapy with anti-CD38 monoclonal antibodies was in the order of weeks for evidence of response." (PMID 35955734, 2022).